BDNF (brain derived neurotrophic factor)
Diseases named in the same sentence as BDNF in open-access papers (continued):
Sharing a sentence is not in itself a finding about the gene and the disease.
Cognitive impairment (continued). "In aged rats, it is reported that sodium butyrate (histone deacetylase inhibitor) not only reverses the signaling changes including down-regulation of HDAC2 and restoration of BDNF expression but also rescues cognitive impairment caused by repeated isoflurane exposure." (PMID 30341248, 2019). "This study was to determine whether altered serum BDNF levels and cognitive deficits depended on the BDNF Val66Met polymorphism in T2DM." (PMID 29423073, 2018). "BDNF gene Val66Met variation may be associated with cognitive deficits in T2DM, especially with delayed memory." (PMID 29423073, 2018). "The results showed that a decrease in plasma BDNF levels and cognitive impairment may be caused by occupational Mn exposure." (PMID 30068329, 2018). "In addition, epidemiological studies showed that low serum levels of BDNF are associated with the motor and cognitive impairments in parkinsonian patients." (PMID 30524223, 2018). "In particular, Tumor Necrosis Factor-α (TNF-α) may interact with BDNF and cause cognitive impairment." (PMID 29896133, 2018). "The abnormality in BDNF signalling pathway in alcohol dependence may cause the cognitive impairment and brain atrophy." (PMID 29520063, 2018). "Furthermore, the association of serum BDNF level with cognitive impairment in T2DM patients was moderated by the BDNF-Val66Met polymorphism." (PMID 29423073, 2018). "Hence, the association between cognitive impairment and the BDNF Met variant in T2DM will need to be confirmed in the future studies in different ethnicities, for instance, in Caucasian population." (PMID 29423073, 2018). "Recently researches have shown that the expression level of BDNF was correlated with the seriousness of the cognitive impairment, and these results suggest that the reduction of BDNF may play an early cofactor in memory abilities loss and cognitive impairment." (PMID 29190943, 2017). "The effect of powder diet was less than molar loss, but long-term conditions of molar loss and powder diet might lead to decreased BDNF and TrkB mRNA levels and pyramidal cells, resulting in cognitive impairment." (PMID 27919226, 2016). "A previous study proposed that BDNF could be a diagnostic biomarker in patients with early Alzheimer’s disease and mild cognitive impairment." (PMID 27483466, 2016). "This could explain some cognitive deficits, as reduced BDNF levels have been associated with impaired cognition." (PMID 26509097, 2015). "Our working hypothesis claimed that BDNF deficiency should accelerate the onset of cognitive impairment and amplify the cognitive deficits displayed by the APP/PS1-mice." (PMID 25852506, 2015). "Much evidence has accumulated indicating that BDNF-TrkB signaling declines in AD patients and in patients with mild cognitive impairment, and this deficient signaling may even precede the decline of choline acetyltransferase (ChAT) activity." (PMID 26262618, 2015). "Val66Met polymorphism of BDNF may be associated with increased risk for cognitive impairments and is mediated at least in part by activity-dependent trafficking and/or secretion of BDNF." (PMID 25414642, 2014). "It was found that a single injection of EI caused transient cognitive impairment in rats, which may be due to the downregulation BDNF expression, which is similar to the results observed with isoflurane." (PMID 25009603, 2014). "We investigated whether plasma BDNF levels are associated with cognitive impairment in patients with a first psychotic episode." (PMID 23320462, 2013). "Their results suggest that deficiency in pro-BDNF processing might be a possible biological mechanism underlying schizophrenia with cognitive impairment." (PMID 23785335, 2013). "The aim of this study is to investigate whether Brain Derived Neurotrophic Factor (BDNF) levels are associated with cognitive impairment in FEP patients compared with healthy controls." (PMID 23320462, 2013).
Cognitive impairment (continued). "Our results suggest that BDNF is associated with the cognitive impairment seen after a FEP." (PMID 23320462, 2013). "A functional polymorphism (Val66Met) in the pro-region of BDNF, which affects the intracellular trafficking of proBDNF has been associated with memory and cognitive deficits as well as to an increased susceptibility for several psychiatric disorders especially those with a neurodevelopmental origin." (PMID 20141627, 2010). "However, muscle wasting causes postoperative cognitive impairment in rats by reducing BDNF." (PMID 40535513, 2025). "In addition, the cognitive impairment caused by rotenone exposure that we observed in this study may also be due to decreased hippocampal BDNF expression." (PMID 40208367, 2025). "In addition, the BDNF Val66Met polymorphism may be a major factor in the susceptibility to cognitive impairment which affects the secretion of mature BDNF." (PMID 38648255, 2024). "For those who advocate the presence of cognitive deficits in NCB, the adverse effects of burnout on cognition might be associated with a decrease of the brain-derived neurotrophic factor, which would disrupt brain functioning and lead to cognitive deficits even in the early stages of burnout." (PMID 38397729, 2024). "BDNF Val is considered a risk allele for patients with poststroke dementia, and it was found that ischemic stroke patients with a heterozygous Val/Met genotype developed cognitive impairment earlier than those with a Met/Met homozygous genotype and had significantly reduced survival." (PMID 38845616, 2024). "Additionally, ketamine can prevent cognitive impairment and neurodegeneration associated with anesthesia in developing brains by inhibiting inflammation-mediated toxicity and promoting synaptic plasticity by releasing brain-derived neurotrophic factor (BDNF)." (PMID 39219957, 2024). "Overall, the evidence of increased prevalence of cognitive impairment and neuropsychiatric disorders in DM patients in one hand, and the role of BDNF in mediating glucose-associated metabolic pathways in the other hand imply that DM might impact the maintenance of BDNF levels in body fluids." (PMID 36787304, 2023). "Of note, BDNF-dependent signalling has repeatedly been implicated as mediating the beneficial effects of environmental enrichment, and one agonist for the BDNF TrkB receptor, 7,8-dihydroxyflavone, is reported to be efficacious in a range of experimental models of cognitive impairment." (PMID 37432063, 2023). "In addition, it has also been demonstrated that cytokines and brain-derived neurotrophic factor (BDNF) levels may be associated with the development of T2DM-related cognitive impairment." (PMID 37113152, 2023). "Indeed, in AD, the hippocampus is one of the first areas of the brain to be affected, and it is thought that the loss of BDNF in this brain region may contribute to the cognitive impairment observed in AD patients." (PMID 37109038, 2023). "Thus, the regulation role of SIRT1 on BDNF via different signaling pathways may be a potential mechanism by which SIRT1 improves cognitive impairment associated with chronic pain, which need to be further researched." (PMID 37592394, 2023). "In addition, reports suggest that cognitive deficit related to amphetamine neurotoxicity may be associated with changes in brain-derived neurotrophic factor (BDNF) in the hippocampus in the METH-induced model of mania in rats." (PMID 36594063, 2023). "However, it remains unclear whether and how the hippocampal BDNF-trkB pathway is causally involved in ELS-induced cognitive deficits." (PMID 37225683, 2023). "Therefore, we hypothesized that vHipp neurons projecting to the IL may be responsible for BDNF-associated plasticity necessary for extinction to reverse stress-induced cognitive deficits in set shifting." (PMID 37480574, 2023).
Cognitive impairment (continued). "Intrahippocampal infusions of TAT-Pep5 and exogenous administration of BDNF could attenuate surgery-induced cognitive deficits via tuning the ratio of BDNF/proBDNF and alleviate the deficiency of synaptic function, which is supposed to be a potential therapeutic target in future POCD prevention." (PMID 35370607, 2022). "Thus, high levels of BDNF are associated with lower risk of cognitive impairment in AD patients." (PMID 35692417, 2022). "In addition to mediating exercise's positive effects on cognition, these proteins have been shown to rescue cognitive deficits associated with neurodegenerative diseases such as Alzheimer's disease by inducing BDNF signaling as well as behavioral deficits observed in mouse models of depression." (PMID 34108925, 2021). "Therefore, to elucidate whether cognitive impairment influences the salivary metabolic profile, we investigated the changes in salivary metabolites associated with altered hippocampal BDNF expression levels using a cerebral ischemia mouse model." (PMID 33920851, 2021). "Reduced BDNF mRNA levels are found in the hippocampus and frontal cortex of patients with AD, suggesting that BDNF depletion or deficiency may contribute to the cognitive deficits in these patients." (PMID 35008438, 2021). "Indeed, it has been shown that low serum BDNF levels are linked to increased cognitive impairment." (PMID 32397504, 2020). "With respect to neurotrophic factors, a link between BDNF, exercise, and cognition has been proposed during aging, suggesting that this association may have a critical role for the prevention and minimization of cognitive impairment during aging." (PMID 33584215, 2020). "Thus we speculate that BDNF Met/Met genotype could cause these cognitive impairments by modulating the hippocampus or prefrontal function." (PMID 33047489, 2020). "Furthermore, low BDNF is associated with cognitive impairment in DM patients." (PMID 32405353, 2020). "First, we only explored the association between BDNF Val66Met SNP and cognitive impairments in PD patients; however, it is unknown whether other BDNF SNPs such as rs11030104 and rs7103411 could be involved in BNDF plasma Levels and cognitive defects in PD patients." (PMID 33047489, 2020). "Oroxylin A reduced cognitive impairment caused by permanent occlusion of bilateral common carotid arteries (2VO) via inhibiting activated microglia and enhancing expression of brain derived neurotrophic factor (BDNF) and cAMP response element-binding protein (CREB)." (PMID 33147823, 2020). "Therefore, we postulate that the protective effect of BDNF Val66Met polymorphism on cognitive impairment is conditional on the presence of active malignancy or ongoing cancer treatment, both which have been hypothesized as possible causes of CRCI." (PMID 30382534, 2019). "Furthermore, findings from a longitudinal study of 145 early-stage breast cancer patients suggested that carriers of BDNF Met allele could protect cancer patients against post chemotherapy cognitive impairment." (PMID 29864112, 2018). "Thus, it is likely that the specific role of the BDNF Met allele in cognitive deficits, especially delayed memory in T2DM patients may be limited to Chinese or Asian populations, which may not be adapted to the western patients." (PMID 29423073, 2018). "In fact, loss of proBDNF and BDNF occurs early in the disease course (before plaque deposition) and correlates with memory deficits, strongly suggesting the relevance of those changes for the synaptic loss and cell dysfunction underlying AD cognitive impairment." (PMID 28134845, 2017). "Heroin addiction has a series of cognitive impairments that may be associated with BDNF." (PMID 28403087, 2017). "Thus, the BDNF Val66Met polymorphism, which modulate BDNF secretion, might be associated with cognitive impairment in BD31." (PMID 27905499, 2016).
Cognitive impairment (continued). "BDNF is a neurotrophin widely expressed in the brain where it is implicated in neuronal growth, synaptic plasticity, and neuronal survival, and it plays important roles in structural brain abnormalities observed in depressed individuals, such as reduced hippocampal volume or cognitive deficits." (PMID 26005424, 2015). "The present experiments may provide such novel evidence that the beneficial effects of DHA on cognitive impairment in rats with metabolic syndrome is associated with the restoration of molecular systems, including BDNF, which regulates synaptic plasticity to enhance memory." (PMID 23963508, 2013). "They reported that db/db mice had neuropsychiatric symptoms such as cognitive deficits and anxiety-like behaviors and that the symptoms were associated with increased inflammatory cytokines and reduced expression of brain-derived neurotrophic factor (BDNF) in the hippocampus." (PMID 23082896, 2012). "Previous studies have demonstrated that transgenic BDNF expression in the brain can promote neurogenesis, elicit anxiolytic-like activities, and alleviate cognitive impairment in AD rodent models." (PMID 41480410, 2026). "Serum BDNF and IGF-1 were analyzed using enzyme-linked immunosorbent assay and chemiluminescent immunoassay, and cognitive status was evaluated using the Cognitive Impairment Screening Test (CIST)." (PMID 42072914, 2026). "We focus on the potential of BDNF activators, such as TrkB agonists and mimetic molecules, to restore synaptic function and ameliorate cognitive deficits in AD." (PMID 40380033, 2025). "LSDF outperformed HSDF in improving cognitive deficits, reversing weight loss, lowering DAI scores, and restoring colon length and tissue structure, with better effects on serum LPS and BDNF levels." (PMID 40077572, 2025). "Our findings demonstrate that enhanced PA levels are associated with both improved sleep quality and attenuated next-day cognitive impairment, potentially mediated through upregulated BDNF production." (PMID 40950772, 2025). "Combined use of soybean embryo ethanol extract and Lactobacillus gasseri NK109 potently enhanced hippocampal BDNF expression, and the number of BDNF-positive neuron cells, while reducing LPS-induced cognitive impairment and colitis in mice." (PMID 40697274, 2025). "Altered levels of neurotrophins such as NGF, BDNF, NT3, and NT4, as well as growth factors like IGF1, VEGF, and FGF, have been associated with cognitive deficits, sensory processing abnormalities, and behavioral issues in ASD patients." (PMID 40004071, 2025). "After 5 weeks of administration, C29 reduced cognitive impairment and restored the expression of key neurogenic and anti-inflammatory markers, including brain-derived neurotrophic factor (BDNF), doublecortin (DCX), and cAMP response element-binding (CREB)." (PMID 40636703, 2025). "Salivary biomarkers, particularly BDNF, have emerged as promising indicators of neuroplasticity in populations with cognitive impairment." (PMID 41146751, 2025). "The clinical effects of vitamin D supplementation and its concentration on BDNF are more pronounced in their effects on mood than on cognition impairment." (PMID 40871684, 2025). "Altogether, the findings indicate that ROE restores hippocampal CREB/BDNF signaling and mitigates neuroinflammation, positioning it as a promising candidate for managing cognitive impairment related to neuroinflammation and neurodegenerative conditions." (PMID 41155671, 2025). "In this context, it has been assumed that the pathological changes in pwMS leading to cognitive impairment are compensated through hippocampal hyperactivation, potentially related to higher BDNF levels, to preserve episodic memory." (PMID 39812717, 2025). "A study on scopolamine-induced cognitive deficits in animals showed that scopolamine injection decreased BDNF concentrations in hippocampal tissue." (PMID 40871684, 2025).
Cognitive impairment (continued). "This study demonstrated that niacin plays an important role in the prevention of WBI-induced behavioral and cognitive impairment by activating the CREB/BDNF signaling pathway." (PMID 40508105, 2025). "Another anti-IS drug, β-Caryophyllene, ameliorates cognitive impairment after IS through the cAMP/PKA/CREB/BDNF pathway in MCAO mice." (PMID 40692577, 2025). "PM10 exposure decreased the expression in the region of the hippocampus of Brain-Derived Neurotrophic Factor (BDNF), which plays a crucial role in memory consolidation and cognitive function; its reduction is linked to schizophrenia's cognitive impairments." (PMID 39803412, 2025). "Exercise has been shown to increase Sirt1 and BDNF levels, positively impacting aging-induced cognitive impairment and improving brain function." (PMID 41154548, 2025). "The results showed that calcitriol supplementation increases BDNF content in the hippocampus of rats and alleviates cognitive disorders." (PMID 40358165, 2025). "Another study from Australia reported that a 12-week Qigong program led to enhanced cognitive function and increased brain-derived neurotrophic factor levels in older adults with mild cognitive impairment." (PMID 40342973, 2025). "Third, we did not assess cognitive function directly, so we cannot conclude that the observed changes in hippocampal BDNF signaling translate into cognitive impairments." (PMID 40960371, 2025). "Future studies are also recommended to elucidate the role of many other neurotrophic factor levels, myelination, and BDNF in oligodendrocytes in the therapeutic effect of QET in SD‐induced cognitive impairments." (PMID 39829139, 2025). "Germ-free mice show significant cognitive deficits, impaired memory, and learning, alongside reduced hippocampal BDNF expression, disrupted synaptic plasticity, and abnormal spine morphology." (PMID 40909931, 2025). "Studies suggest that chemotherapy can disrupt the balance of pro- and anti-inflammatory cytokines, as well as reduce BDNF expression, which contributes to neuroinflammation and subsequent cognitive impairment." (PMID 41155372, 2025). "This systematic review (osf.io/vk37x) addresses the use of BDNF and cytokines as biomarkers of cognitive impairment in breast cancer animal models." (PMID 41155372, 2025). "The distinct biological profiles observed in the SIC and GIC groups – characterised by differences in BDNF and CRP levels – highlight the complexity of the mechanisms underlying cognitive impairments in bipolar disorder." (PMID 41367212, 2025). "Lou and colleagues administered Aβ1–42 for AD induction, resulting in alterations typical for AD with decreased BDNF and cognitive impairment." (PMID 40430064, 2025). "Taken together, activators of BDNF signaling have crucial roles in mitigating memory and cognitive impairment in AD." (PMID 40380033, 2025). "And multicomponent training in individuals with mild cognitive impairment (MCI)/dementia provided a cognitive SMD ≈ 0.4 with a proportional increase in BDNF." (PMID 40871684, 2025). "Stress, on the other hand, can alter NGF and BDNF levels, resulting in cognitive impairment and mood disorders." (PMID 40572619, 2025). "Simultaneously, insulin resistance impairs intracellular BDNF signalling, exacerbating cognitive deficits." (PMID 40566596, 2025). "Findings from clinical studies observed that ApoE4 carriers had progressive cognitive impairment and low BDNF expression in AD patients." (PMID 40380033, 2025). "According to the AUROC analysis, BDNF is recognized as a reliable biomarker for the assessment of cognitive impairment in this group, with an AUROC value of 0.8550." (PMID 40291844, 2025). "Despite these limitations, our findings demonstrate complex interactions between peripheral BDNF methylation status, gene and protein levels, BDNF Val66Met genotype, and cognitive impairments, which have been so far hard to interpret." (PMID 41009553, 2025).